SNPH (syntaphilin)
Description:
Inhibits SNARE complex formation by absorbing free STX1A.
Synonyms: bA314N13.5
Tractability: Antibody: UniProt predicts a signal peptide or a membrane-spanning region. PROTAC: ubiquitination databases record sites on it; its protein half-life has been measured.
Gene: Protein-coding gene on chromosome 20 (1,266,269 to 1,309,328, forward strand). Ensembl gene ENSG00000101298.
Subcellular location: Membrane; Synapse, synaptosome
Subcellular location (Human Protein Atlas): Mitochondria; Cytokinetic bridge
Gene Ontology:
Molecular function: protein binding; syntaxin-1 binding
Biological process: neuron differentiation; neurotransmitter secretion
Cellular component: cytoplasm; cytoplasmic microtubule; mitochondrion; membrane; presynapse; synapse
Genetic constraint (gnomAD): Loss-of-function variants: 11 observed, 36.71 expected, observed/expected ratio (o/e) 0.3, 90% interval 0.19 to 0.5. The upper end of that interval is the gene's LOEUF score, 0.5, which puts it in group 2 of 6, group 1 being the genes least tolerant of losing a copy. Missense variants: 622 observed, 732.15 expected, observed/expected ratio (o/e) 0.85, 90% interval 0.8 to 0.91. Synonymous variants: 281 observed, 303.41 expected, observed/expected ratio (o/e) 0.93, 90% interval 0.84 to 1.02.
Homologues: Orthologues: rabbit SNPH (91% identical), pig SNPH (91% identical), macaque SNPH (90% identical), rat Snph (90% identical), guinea pig SNPH (84% identical), mouse Snph (84% identical), tropical clawed frog SNPH (48% identical), zebrafish snphb (46% identical), zebrafish snpha (21% identical). Paralogues in human: SYBU (38% identical).
Diseases named in the same sentence as SNPH in open-access papers:
SNPH is named in the same sentence as 13 diseases in open-access papers, as found by Europe PMC text mining. Sharing a sentence is not in itself a finding about the gene and the disease. The quoted sentences say what the papers report.
breast carcinoma (2 papers, 2022 to 2025). "Together, our findings describe a new α7 nAChR-S100A8/A9-Syntaphilin immune signaling module that drives nicotine-induced tumor progression and distinguishes smoking-related patient disease as a distinct subset of aggressive breast cancers." (PMID 39856330, 2025). "Interestingly, several other HDAC1/7-SE upregulated targets, such as SNPH, CCANG4, PREX1, IGFBP5, IL34 and BCAS4 also demonstrate remarkable level of breast cancer associated over-expression, providing additional support for the relevance of the ET-125 signature." (PMID 36038558, 2022).
depression (1 paper, 2020). "Also, RAB14 expression in human brain tissue has been linked to depression and suicide, as was Syntaphilin, a protein that regulates synaptic vesicle processing and encoded by SYNPH, a gene associated to one of the top 10 CpG sites from the meta-analysis." (PMID 31992121, 2020).
lung carcinoma (1 paper, 2015). "For example, the Syntaphilin protein, encoded by SNPH harbors the syntaphilin domain instance, which was significantly mutated in lung cancer." (PMID 25794154, 2015).
subarachnoid haemorrhage (1 paper, 2016). "The morphological discrepancies between iNPH and sNPH lead us to conclude that the pathogenesis of iNPH is markedly different from the developmental process of sNPH following subarachnoid haemorrhage or brain injury." (PMID 27941913, 2016).
tumor (7 papers, 2016 to 2025). "As a negative regulator of this pathway, SNPH acts as a conceptually novel ‘metastasis suppressor', progressively downregulated or lost during tumour progression, and associated with heightened mitochondrial dynamics, increased tumour cell invasion and shortened patient survival." (PMID 27991488, 2016). "The first report examining MIRO2 in cancer showed that MIRO2 depletion partially reduced tumor cell invasion in PCa cells; however, MIRO2 was dispensable for exacerbated tumor cell invasion induced by depletion of Syntaphilin." (PMID 39128718, 2024). "Downregulation of Miro1 expression was found to regulate negatively tumor cell invasion in syntaphilin knock-down cancer cells." (PMID 35959487, 2022). "Mechanistic studies hint that SNPH is modified by the ubiquitin ligase CHIP/STUB1 and deubiquitinated in a USP7-dependant manner, which suggeststhat ubiquitination of SNPH isa pivotal regulator of mitochondrial trafficking and tumor cell invasion." (PMID 33498743, 2021). "Depletion of mitochondrially localized syntaphilin increases the number of cells with G2/M DNA content, thereby decreasing the proliferation of tumor cells." (PMID 35186947, 2021). "Tumor cells under the influence of hypoxia downregulate SNPH protein and mRNA levels, which inturn leads to increased invasiveness in glioblastoma cells." (PMID 33498743, 2021). "Syntaphilin (SNPH) is a molecule that is capable of inhibiting mitochondrial trafficking and is a regulator of tumor metastasis." (PMID 33233365, 2020). "In neurons, SNPH works in concert with a network of molecules that control mitochondrial trafficking 17, and a role of this network in tumour cell movements was next investigated." (PMID 27991488, 2016). "Here, the authors demonstrate the reprogramming of a neuronal network of mitochondrial trafficking in tumor cells, and identify Syntaphilin as a key protein that suppresses organelle dynamics thereby blocking chemotaxis and metastasis in mice." (PMID 27991488, 2016). "Furthermore, we have found that depletion of the mitochondrial anchoring protein Syntaphilin resulted in dramatic redistribution of mitochondria toward the cortical region of cancer cells and led to exacerbation of tumor cell motility in PCa cell models." (PMID 39128718, 2024). "Lowering of syntaphilin (SNPH), a neuronal cytoskeletal protein that regulates mitochondrial movement causes relocalization of mitochondria from perinuclear position to the cortical cytoskeleton and leads to increased tumor cell motility." (PMID 35186947, 2021). "Using a genome-wide shRNA screen, we now show that tumours reprogram a network of mitochondrial dynamics operative in neurons, including syntaphilin (SNPH), kinesin KIF5B and GTPase Miro1/2 to localize mitochondria to the cortical cytoskeleton and power the membrane machinery of cell movements." (PMID 27991488, 2016). "Syntaphilin is a negative regulator of tumor cell migration and invasion, and the protein is connected with the tubulin transport of vesicles and was formerly thought to play a role exclusively in neurons; however, recent research revealed that it may be functional in other cell types." (PMID 35959487, 2022).
cancer (6 papers, 2017 to 2025). A tumor composed of atypical neoplastic, often pleomorphic cells that invade other tissues. "Recently, the cytoskeletal protein syntaphilin (SNPH), known for arresting mitochondrial movement at sites of high energy demands, was found to be expressed in cancer." (PMID 32674438, 2020). "We also discovered Syntaphilin (SNPH) as an S100A8/A9-dependent gene enriched specifically in estrogen receptor-negative (ER-) cancers from former smokers, linking this response to patient disease." (PMID 39856330, 2025).
SNPH also shares sentences with these, for which no sentence is quoted: breast adenocarcinoma (1 paper); epilepsy (1); glioblastoma (1); neuroblastoma (1); prostate carcinoma (1); psychosis (1); schizophrenia (1).